SSNA1 (SS nuclear autoantigen 1)
Description:
Microtubule-binding protein which stabilizes dynamic microtubules by slowing growth and shrinkage at both plus and minus ends and serves as a sensor of microtubule damage, protecting microtubules from the microtubule-severing enzyme SPAST. Induces microtubule branching which is mediated by the formation of long SSNA1 fibrils which guide microtubule protofilaments to split apart from the mother microtubule and form daughter microtubules (By similarity). Plays a role in axon outgrowth and branching. Required for cell division.
Synonyms: NA14; N14; NA-14
Tractability: Antibody: its Gene Ontology location is reachable by antibodies, with medium confidence. PROTAC: ubiquitination databases record sites on it.
Gene: Protein-coding gene on chromosome 9 (137,188,657 to 137,190,370, forward strand). Ensembl gene ENSG00000176101.
Subcellular location: Nucleus; Cytoplasm, cytoskeleton, microtubule organizing center, centrosome; Cytoplasm, cytoskeleton, microtubule organizing center, centrosome, centriole; Midbody; Cytoplasm, cytoskeleton, flagellum basal body; Cytoplasm, cytoskeleton, flagellum axoneme; Cell projection, axon
Subcellular location (Human Protein Atlas): Basal body; Nucleoplasm; Cytosol; Vesicles
Pathways (Reactome):
Cell Cycle: AURKA Activation by TPX2; Loss of Nlp from mitotic centrosomes; Loss of proteins required for interphase microtubule organization from the centrosome; Recruitment of NuMA to mitotic centrosomes; Recruitment of mitotic centrosome proteins and complexes; Regulation of PLK1 Activity at G2/M Transition
Organelle biogenesis and maintenance: Anchoring of the basal body to the plasma membrane
Gene Ontology:
Molecular function: identical protein binding; microtubule binding; protein binding
Biological process: axon arborization; axon extension; cell division; microtubule cytoskeleton organization; microtubule nucleation; axonogenesis
Cellular component: axoneme; centriole; centrosome; ciliary basal body; midbody; supramolecular fiber; axon; cytosol; nucleus
Genetic constraint (gnomAD): Loss-of-function variants: 13 observed, 11.42 expected, observed/expected ratio (o/e) 1.14, 90% interval 0.74 to 1.75. The synonymous counts are far from expectation, so gnomAD's model fits this gene poorly and the ratio says little. Missense variants: 186 observed, 153.14 expected, observed/expected ratio (o/e) 1.21, 90% interval 1.08 to 1.37. Synonymous variants: 89 observed, 66.51 expected, observed/expected ratio (o/e) 1.34, 90% interval 1.13 to 1.6.
Homologues: Orthologues: chimpanzee SSNA1 (100% identical), macaque SSNA1 (99% identical), mouse Ssna1 (97% identical), pig SSNA1 (97% identical), dog SSNA1 (96% identical), guinea pig SSNA1 (96% identical), rat Ssna1 (83% identical).
Diseases named in the same sentence as SSNA1 in open-access papers:
SSNA1 is named in the same sentence as 9 diseases in open-access papers, as found by Europe PMC text mining. Sharing a sentence is not in itself a finding about the gene and the disease. The quoted sentences say what the papers report.
Sjögren's syndrome (3 papers, 2012 to 2025). "Spastin interacts in cells with the NA14 protein, a major target for auto-antibodies in Sjögren's syndrome (nuclear autoantigen 1; SSNA1)." (PMID 25390646, 2014). "Spastin interacts with the centrosomal protein NA14, a major btarget for auto-antibodies in Sjögren's syndrome (nuclear autoantigen 1, SSNA1)." (PMID 25390646, 2014). "The SSNA1 protein was originally identified as an autoantigen from a single Sjögren's syndrome patient and a recent study showed that 14% of PSS cases tested positive for autoantibodies against this protein, compared to 2% or less of patients with other rheumatoid diseases." (PMID 22363749, 2012). "NA14 (also known as SSNA-1 due to its role in primary Sjögren’s syndrome, a chronic autoimmune disease) has not been directly classified as a ciliopathy-associated protein." (PMID 41364719, 2025).
leukemia (1 paper, 2022). A malignant (clonal) hematologic disorder, involving hematopoietic stem cells and characterized by the presence of primitive or atypical myeloid or lymphoid cells in the bone marrow and the blood. "There were many leukemia-related genes in the up-regulated genes of K1 group, such as UBB (P=1.56e-50), MIF (P=2.76e-50), DRAP1 (P=1.72e-49), RPS25 (P=1.9e-49), EIF3K (P=4.77e-49), SSNA1 (P=1.27e-48), GPX4 (P=3.01e-48), PHB2 (P=7.13e-48), NME2 (P=2.44e-47) or CFL1 (P=4.07e-47)." (PMID 36408189, 2022).
SSNA1 also shares sentences with these, for which no sentence is quoted: autoimmune disease (1 paper); ciliopathies (1); liver cirrhosis (1); pancreatic cancer (1); rheumatic disease (1); systemic lupus erythematosus (1); T-cell acute lymphoblastic leukemia (1).